LYZ (lysozyme)
Diseases named in the same sentence as LYZ in open-access papers (continued):
Sharing a sentence is not in itself a finding about the gene and the disease.
infection (continued). "Similarly, vaccination with inactivated A. hydrophila vaccine by intraperitoneal injection or immersion shows significant up-regulation of the skin mucus lysozyme and specific antibody levels in the serum and skin of Piaractus mesopotamicus, thereby increasing the survival rate post infection." (PMID 36969197, 2023). "However, the C-type lysozyme in all of the examined tissues in this study was significantly (p < 0.05) expressed post-infection, indicating that the innate system of BI-vaccinated fish was elicited and provided a certain degree of disease resistance and protection against bacterial infections." (PMID 36138746, 2022). "A lysozyme inhibition is a clear signal of alteration of the hemocyte bactericidal competence, which might expose organisms to higher risks for host colonization or infection." (PMID 33800064, 2021). "However, we could not detect a significant reduction of A. laibachii zoosporangia germination upon treatment with active GH25 lysozyme, suggesting that the GH25 lysozyme interferes with A. laibachii at a later stage of infection." (PMID 33427195, 2021). "Besides the enzymatic activity of lysozyme (muramidase), lysozyme could also be helpful as an antimicrobial agent, because it disrupts bacterial membranes, thus controlling the infection, and is, therefore, a promising enzyme for treating biofilms." (PMID 33740161, 2021). "Additionally, the lysozyme and phagocytic activity and, serum antibody (IgM) were significantly higher (P < 0.05) against S. iniae and A. hydrophila in vaccinated groups compared to the unvaccinated group in the pre- and post-infection." (PMID 32615969, 2020). "Therefore, larvae may use crowding as a cue to induce lysozyme expression to protect against possible infection." (PMID 27575006, 2016). "Therefore, infection with B. bassiana may have influenced the expression pattern of the lysozyme gene in larvae reared at the three different densities." (PMID 27575006, 2016). "The sigJ transcript level also increases in late stationary M. tuberculosis cells and in MAP after either infection of Caco2 intestinal epithelial cells or growth in medium supplemented with mycobactin J and lysozyme (a medium that may mimic intracellular stresses;)." (PMID 26445268, 2015). "Therefore, a lack of correlation with C. forsteri infection may also suggest limited effect of infection on lysozyme and alternative complement activity." (PMID 23029217, 2012). "Though we depleted the most abundant plasma proteins in infection challenge samples, our proteomics analysis identified relatively abundant proteins such as APOC3 and lysozyme." (PMID 41326716, 2026). "Elevated lysozyme, AKP, and ACP suggested activation of the innate immune system in response to infection, while the increase in SOD and GSH-Px represented a compensatory antioxidant response to oxidative stress." (PMID 41007974, 2025). "We first evaluated lysozyme expression in mice at homeostasis and after 108 CFU S. Typhimurium (SL1344) infection via oral gavage." (PMID 38823640, 2024). "We found that infection with the wild type strain triggered the expression of the four antimicrobial peptides tested here (gallerimycin, galliomycin, IMPI, and lysozyme)." (PMID 35208772, 2022). "After infection with DIV1, the activity of LYZ in the intestine of M. japonicus was significantly decreased, which indicated that the intestinal immune function was suppressed to some extent." (PMID 36189245, 2022). "This was also observed with the antimicrobial effector lysozyme, where LYSC and LYSB induction levels during infections with B. brongniartii lagged those observed with B. bassiana and I. javanica infections at the early stages of infection (3 dpi)." (PMID 36687607, 2022).
infection (continued). "The current study identified a statistically significant decrease in lysozyme in the KCS dogs, indicating not only a decrease in lacrimal gland synthesis but also reduced lysozyme could lead to an increased predisposition to the development of infection in the ocular surface." (PMID 34316222, 2021). "In the second experiment, as in the case of lysozyme activity, the group previously infected with IPNV reacted to the simulation of infection more strongly than the control group." (PMID 34359116, 2021). "After infection at 12 h (EI12H), a total of 15 AMP genes including lysozyme, VIP.3, and YFGAP.4 exhibited up-regulation." (PMID 34681113, 2021). "After infection with DIV1 at 24 hpi, the activities of SOD, CAT, LYZ, and PO in the plasma were detected to evaluate the effect of DIV1 infection on the immune enzymes of M. japonicus." (PMID 34512588, 2021). "Secretion of IL-10 in response to infection with the parental strain was mostly TLR2-dependent, while IL-10 secretion in response to lysozyme-sensitive strains was dependent on TLR2 and Unc93b1." (PMID 32634175, 2020). "After infection, mortality was delayed in fish fed GRA, which also revealed increased lysozyme activity levels, as well as decreased lipid peroxidation, suggesting higher antioxidant capacity than in fish fed a control diet." (PMID 31695116, 2019). "The increased lysozyme and IgY allocation may however explain why the reproductive success of great tits was only moderately lower than that of blue tits, despite their larger infection pressure and the observed correlation between infection pressure and hatching failure." (PMID 30286089, 2018). "Fish fed MET 1 showed higher lysozyme activity at 24 and 48 h whereas fish fed MET 0.5 presented an increased activity at 48 h after infection compared to fish fed CTRL." (PMID 30524433, 2018). "Plasma lysozyme, peroxidase, ACH50, and bactericidal activities of European seabass fed dietary treatments at 4 weeks (0 h), 4, 24, and 48 h after infection." (PMID 30524433, 2018). "Lysozyme, ixoderin, and peptidoglycan recognition protein (PGRP) CDSs were upregulated by infection in both tick species." (PMID 28503490, 2017). "We measured the expression level of the lysozyme gene DcLys-4 and found that, like PPO, it was significantly upregulated (P<0.05) by 2.81-fold on the first day of infection, 17.37-fold on the third day, and 27.00-fold on the fifth day." (PMID 27644092, 2016). "In contrast, only three immune related genes, one lysozyme and two involved in NOS (nitric oxide synthases) pathway, were identifed in the hemocytes after infection, all of which were up-regulated." (PMID 26503342, 2015). "Thus, there would be no immediate need to reverse their up-regulation once the infection is resolved, unlike the case of lysozyme-encoding genes, which could potentially damage host cells." (PMID 25340560, 2014). "All genes play major roles in immune response during infection including cytokines (IL8, IL6, IL10, IL1B, and TNF) and SAA3 (an acute-phase protein), as well as PMN adhesion selectin-L (SELL) and LYZ (involved in anti-microbial defense)." (PMID 19925655, 2009). "A number of additional genes that play important roles in the immune response to infection were also increased in expression in response to trypanosome infection (GZMB, LYZ, CYBB and NCR3)." (PMID 19409086, 2009). "In LA-4 cells, infection with B. pseudomallei resulted in significant down-regulation of lysozyme and significant up-regulation of CCL20 and SLPI at 6 h and 24 h post infection compared to uninfected control cells (p<0.05)." (PMID 19806192, 2009). "Pre-incubation of the epithelial cells with BAY11-7082 (10 μM) significantly impaired the up-regulation of all three CCL20, lysozyme and SLPI genes upon B. pseudomallei KHW infection compared to untreated cell controls (p<0.05)." (PMID 19806192, 2009).
infection (continued). "The expression of the antimicrobial peptide genes, lysozyme, CCL20 and SLPI, at 4 h, 24 h, 48 h and 72 h post infection was determined using qRT-PCR." (PMID 19806192, 2009). "Among the non-specific immune indicators, such as lysozyme, myeloperoxidase, and alkaline phosphatase activities, LZM, a non-specific protein-based defense factor, plays an important role in aquatic animal resistance to pathogen infection." (PMID 39728130, 2024). "Many Gram-negative bacteria are able to produce lysozyme inhibitors that can significantly inhibited/decrease lysozyme activity in the host serum beginning from the early stages of host infection." (PMID 37731496, 2023). "The study demonstrated that nisin and lysozyme were effective at later stages of the infection, and the intensity of their effect did not diminish with time." (PMID 34943746, 2021). "Fish lysozyme is an enzyme with antibiotic properties and has been considered as an indicator of non-specific immune functions against infections." (PMID 32231137, 2020). "Nevertheless, lysozyme activity in the hemolymph of D. suzukii larvae was not significantly stimulated by the infection of X. nematophila or the bacterial mixture of E. coli and M. luteus (GLM: F = 0.12, df = 2, p = 0.81)." (PMID 32231138, 2020). "Nisin and lysozyme were effective at later stages of infection, and the intensity of their effect did not diminish with time." (PMID 31488163, 2019). "A vaccine containing rDn-ACP could contribute to protection by enabling normal lysozyme function and further studies are needed to examine the role of Dn-ACP in particular during infection in vivo." (PMID 31296905, 2019). "That is, extracellular lysozyme alone should not be able to stop ongoing phage adsorption and infection, else plaques themselves would not be able form." (PMID 31623057, 2019). "Higher lysozyme levels were detected after the race in runners with LRTI when compared with those without infection." (PMID 30462646, 2018). "Ploidy had a significant effect on lysozyme activity at 21 days post-infection (while infection and time did not), although activity was within the ranges previously recorded for salmonids." (PMID 28492111, 2017). "In general, larvae and adults showed a similar level of infection-induced induction of some pathogen recognition and signal modulation genes, as well as some immune effector genes, such as cecropin (CECA), gambicin (GAM1), defensin (DEF1) and lysozyme (LYSC1)." (PMID 28764812, 2017). "Control experiments demonstrated that B cells with BCRs specific for hen egg lysozyme (MD4 Rag2−/− mice) did not bind the MSP1 tetramer nor were they activated non-specifically by Plasmodium 8 days post-infection after adoptive transfer into a congenic host." (PMID 27473412, 2016). "Human lysozyme is a natural non-specific immune factor in human milk that plays an important role in the defense of breastfed infants against pathogen infection." (PMID 25955256, 2015). "The significant changes in histopathological features, apoptotic cells, and enzyme activities (e.g., lysozyme (LYS), alkaline phosphatase (AKP), alanine aminotransferase (ALT), aspartate transaminase (AST), and glutathione peroxidase (GSH-Px)) in the intestine were examined after infection." (PMID 38426108, 2024). "A group of lysozyme genes (like lys-4, lys-6 and ilys-5), C-type lectin genes (like ugt-30, ugt-6, ugt-64 and ugt-53) and UDP-Glucuronosyl transferase genes (like ugt-30, ugt-6, ugt-64 and ugt-53) were also commonly down-regulated by HIF-1 high-activity and P. aeruginosa PA14 infection." (PMID 38517909, 2024). "The lysozyme (LYS), anti-protease (AP), and peroxidase (PER) activities remained stable during the experiment, not showing any important variation; however, in the case of PER activity, a certain downward trend is shown, reaching its peak at 24 h post infection." (PMID 37629124, 2023).
infection (continued). "This may explain why the antibacterial enzyme lysozyme, which is secreted by both the lacrimal gland and phagocytes in the conjunctiva, is suppressed two weeks after infection (p = 0.013) with a non-significant drop during active disease (p = 0.096)." (PMID 37862368, 2023). "At 24 hpi, the activities of SOD, CAT and LYZ in the intestine were detected to evaluate the effect of DIV1 infection on the nonspecific immunity of M. japonicus, and the activities of α-AMS, LPS and TPS in the intestine were detected to evaluate the digestive function." (PMID 36189245, 2022). "Interestingly, amongst the antimicrobial functions analysed upon C. irritans infection, only the serum bactericidal activity was increased, while the natural haemolytic complement, lysozyme, and peroxidase activities were not affected by the infection." (PMID 35055122, 2022). "This might indicate that lysozyme along with other antifungal effectors (i.e., TEP22) comprises the first line of antifungal defense, and that AMPs complement the antifungal repertoire later in the infection process." (PMID 36687607, 2022). "In addition, higher levels of lysozyme were detected after the race in runners with LRTI compared with those without infection." (PMID 30462646, 2018). "Stock and infection did not have a significant effect on lysozyme activity." (PMID 28492111, 2017). "For example, priming induced several novel effector genes, not normally expressed upon infection, like hexamerin, pathogenesis related protein 5, lysozyme and hdd1 defence protein, all with a reported role in defence against orally ingested pathogens and Bacillus thuringiensis." (PMID 28446171, 2017). "In order to elucidate the pathways that are involved in the regulated expression of the antimicrobial peptide genes, lysozyme, CCL20 and SLPI, LA-4 cells were pre-incubated with specific inhibitors of NF-κB and p38 MAPK pathways (BAY11-7082 and SB203580 respectively) prior to the infection process." (PMID 19806192, 2009). "Interestingly, the C-type lysozyme [GI:110762174] that has been previously shown to be up-regulated upon infection is not the lysozyme we have identified here, which is also known as the destabilase-lysozyme [GI: 6656246]." (PMID 19695106, 2009). "The time course of infection was followed in injected (Donors) and non-injected (Recipients) mussels by evaluating presence of V. ostreicida by PCR, responses of hemolymph components (in terms of hemocyte lysosomal stability and lysozyme activity), and histopathological conditions." (PMID 41383590, 2025). "Thus, lysozyme activity was not triggered by the infection X. nematophila nor E. coli/M." (PMID 32231138, 2020). "In the representative assay, it was observed that a 24-h MRSA-infection led to the death of 50% of ARPE-19 cells, which was not rescued by TP or lysozyme monotherapy." (PMID 40912150, 2025). "This may have been correlated with the elevation of nonspecific immune parameters, such as phagocytic activity, lysozyme, NO, C3, and antioxidant enzyme activities, in addition to the reduced levels of glucose and cortisol, which could have strengthened the defense of fish against infection." (PMID 36830534, 2023). "Although glyphosate-exposed honey bees mounted an immune response (based on lysozyme and glucose oxidase genes), those strategies seemed not to be successful, as DWV infection levels increased and honey bee lifespan was significantly shortened." (PMID 33920750, 2021). "The expression of Pen2, Pen3, ALF, Crustin, and Lysozyme during the experiment indicated that the moringa extract, especially at ME2.5, can potentially control the infection of fungi, gram-positive, and gram-negative bacteria." (PMID 35011148, 2021). "Eight of them (FN1, ALB, CTSL1, OTFB, LYZ, CATHL1, MMP9, LECT2) did not change their expression at the level of transcription and transcripts of 3 of them (RSFR, LYG2, CSTC) even increased following infection." (PMID 28623956, 2017).
tumor (132 papers, 1976 to 2026). "Immune infiltration analysis indicated that LYZ expression is linked to specific immune cell types, suggesting its influence on the tumor microenvironment." (PMID 41514850, 2025). "Immune infiltration analysis highlighted significant associations between LYZ expression and specific immune cell types, indicating its potential impact on the tumor microenvironment." (PMID 41514850, 2025). "Thereinto, MPO and lysozyme are specific markers of oral primary GS and are associated with the process of tumor cell differentiation." (PMID 33120806, 2020). "In the tumour microenvironment, genes encoding tumour-related macrophage activities, such as the LYZ (lysozyme), TYMP (thymidine phosphorylase), and CD68 (pan-macrophage) genes, may affect the NLR." (PMID 34997351, 2022). "To validate these results using another methodology, we decided to evaluate if expression levels of STAT1 and LYZ, two genes related to macrophage-signatures and possibly to M1 polarization, might be associated with the tumor microenvironment profile." (PMID 25978381, 2015). "The better survival of NOD2hi COAD patients compared to NOD2lo patients confirms the importance of NOD2 signaling in the immune response against tumor, but may appear at odds with the lower carcinogenesis observed in mice with Nod2 deficiency in lysozyme-expressing myeloid cells." (PMID 37876927, 2023). "The findings demonstrated that tumor cell lines and normal brain glial cells differed significantly in their LYZ gene mRNA levels." (PMID 41514850, 2025). "The LYZ gene was shown to be significantly expressed differently in tumor and normal tissues in the TCGA database, with greater expression levels in the tumor samples." (PMID 41514850, 2025). "LYZ activates macrophages to kill tumors and plays a role in tumor suppression; however, under chronic inflammation, LYZ releases proinflammatory factors (IL-6, TNF-α) to promote immunosuppression in the tumor microenvironment." (PMID 41384115, 2025). "Myeloid and leukemic cells and solid tumor cells also express LYZ, which correlates with tumor prognosis." (PMID 40046560, 2025). "Studies have proved the anti-tumour effects of lysozyme in many types of cancers, possibly through its immunomodulatory effects." (PMID 41383705, 2025). "Next, to address the role of AGK in macrophages in tumor development, we crossed Agkfl/fl mice with lysozyme-Cre (LyzCre) mice to generate Agkfl/fl;LyzCre mice (hereafter, AgkcKO)." (PMID 39816692, 2025). "In our case, CD4, CD68, and CD163 were all positive, and Lysozyme showed a small amount of sporadic positive expression, suggesting that the tumor cells originated from histiocytes." (PMID 40231251, 2025). "fMLP’s anti-tumor activities include macrophage activation and the induction of lysozyme release and pro-inflammatory factors, aiding in tumor cell demise." (PMID 39256638, 2024). "IghelMD4 mice, characterized by over 90% of IgM-secreting B cells specific to chicken egg lysozyme, exhibited a greater tumor burden compared to wild-type (WT) mice in various tumor models." (PMID 38629061, 2024). "Tumor-associated macrophages (TAMs) further divided into monocyte-derived brain macrophages (Mo-TAMs) expressed monocyte markers (TGFBI, VCAN, LYZ, and CLEC12A) and cells termed as Mg-TAMs expressed microglial signature genes (TMEM119, P2RY12, and P2RY13)." (PMID 39451239, 2024). "In the TME, human CD2high pDCs exhibit elevated levels of granzyme B, TRAIL, and lysozyme, which curtail tumor cell proliferation and mediate contact-dependent killing of tumor cells." (PMID 38512518, 2024). "(E) LYZ expression and Paneth cell module scores of single cells in normal, primary tumor, and metastasis samples are presented by dot plots." (PMID 39535280, 2024). "The existence of Paneth‐like cells in GC was further confirmed in the primary tumour sections by RNAscope with the marker genes LYZ and NAMPT." (PMID 35184420, 2022).